NOD1 (nucleotide binding oligomerization domain containing 1)
Diseases named in the same sentence as NOD1 in open-access papers (continued):
Sharing a sentence is not in itself a finding about the gene and the disease.
Insulin resistance (continued). "Nucleotide-binding oligomerization domain 1 (NOD1) or NOD-like Receptor pyrin domain containing 3 (NLRP3) activation promote metabolic inflammation and insulin resistance while NOD2 activation improves insulin sensitivity and glucose homeostasis during obesity." (PMID 41853552, 2024). "Furthermore, nucleotide-binding oligomerization domain-containing protein 1 (NOD1), a widely expressed intracellular receptor for PGN, has been recognized as a pivotal sensor in triggering metabolic inflammation and insulin resistance in diabetes." (PMID 38336763, 2024). "The NOD1/2-/- double knockout (DKO) mice, when fed an HFD, were protected from many of the detrimental effects, including inflammation, lipid accumulation, and peripheral insulin resistance." (PMID 37869013, 2023). "Additionally, a major gap in our understanding is the opposing roles NOD1 and NOD2 play in the control of diet-induced obesity and insulin resistance." (PMID 33503814, 2021). "Regarding NOD1, even if this PRR and exercise training have not yet been directly related, it is clear that NOD1 activation contributes to insulin resistance, cardiac dysfunction, and muscle contraction." (PMID 34066406, 2021). "Because of the recognized contributions of dyslipidemia and inflammation to insulin resistance, we sought to test if TKI-mediated inhibition of RIPK2 could attenuate NOD1-induced impairments in insulin signalling in adipocytes." (PMID 28484277, 2017). "In addition, changes in the diversity of the intestinal microbiota can worsen or improve insulin resistance and therefore type 2 diabetes (T2D) in mice and patients, possibly due to interaction with innate immune signaling through the TLR4, NOD1/NOD2 proteins, etc., as yet undefined pathways." (PMID 34066406, 2021). "Our data show that NOD1 deficient mice fed a HFD for six weeks exhibit an exacerbated increase in lipogenesis in the iWAT and eWAT, but this occurs in the absence of an evident insulin resistance phenotype." (PMID 32704052, 2020). "Unlike NOD1-knockout mice, animals deficient in NOD2 showed no protection to insulin resistance during HFD and even had increased adipose tissue and liver inflammation as well as exacerbated insulin resistance." (PMID 31632962, 2019). "Our current working model proposes that NOD1 deletion is protective, but to the best of our knowledge, no study has shown that defective PGN sensing by NOD2 may interact with a dietary stress to promote worse insulin resistance." (PMID 25666722, 2015). "The exacerbated glucose intolerance and hyperglycemia in HFD-treated Nod1beta-cko mice was not due to insulin resistance, because HFD-treated Nod1 Nod1beta-cko mice were not more insulin resistant than the control mice." (PMID 31201384, 2019). "We previously showed that obese high-fat diet (HFD)-fed mice lacking both nucleotide oligomerization domain (NOD1) and NOD2 have reduced insulin resistance and inflammation." (PMID 25666722, 2015). "This translocation is prevented in mice lacking the microbial recognition receptors NOD1 or CD14, suggesting that these receptors have important roles in the development of the low-grade inflammatory state that characterizes insulin resistance." (PMID 23482058, 2013).
inflammatory bowel disease (26 papers, 2009 to 2025). A spectrum of small and large bowel inflammatory diseases of unknown etiology. "Genetic mutations in both the UPR pathway and NOD1/2 signaling have been linked to increased risk of inflammatory bowel disease (IBD), suggesting that these pathways are connected to both pathogen response and chronic inflammatory disease development." (PMID 34748367, 2022). "It has been revealed that certain genetic NOD1 polymorphisms are associated with a susceptibility to bronchial asthma, atopic dermatitis, and inflammatory bowel disease." (PMID 36146565, 2022). "NOD1 insertion/deletion polymorphism was correlated with and inflammatory bowel disease in Caucasian populations." (PMID 30950247, 2019). "There is no known Nod1-related autoinflammatory disease, but associations between SNPs in NOD1 and several immune-related diseases, such as inflammatory bowel disease, atopic eczema, asthma, and rheumatoid arthritis have been reported." (PMID 29259708, 2017). "Dysregulation of NOD1 and NOD2 signaling has been implicated in inflammatory bowel diseases (IBD), metabolic syndrome, and other immune-related disorders." (PMID 40635891, 2025). "The dynamics associated with these hotspots are crucial for the interaction between RIPK2 and XIAP, a key element in NOD1/2-mediated immune responses, with implications in inflammatory bowel disease and other conditions." (PMID 39190764, 2024). "NOD1, which markedly affects the intestinal flora, is related to the onset of inflammatory bowel diseases in humans." (PMID 36428390, 2022). "NOD1 and NOD2 dysfunction are associated with other chronic inflammatory diseases, such as inflammatory bowel disease (IBD), asthma, arthritis, and periodontitis." (PMID 33503814, 2021). "The NOD1 and NOD2 pathways have been associated with a range of autoimmune disorders, most prominently with inflammatory bowel disease (IBD)." (PMID 31632962, 2019). "For example, NOD1 and NOD2 have been implicated in the pathogenesis of inflammatory bowel disease (IBD)." (PMID 28955343, 2017). "An insertion-deletion polymorphism (ND1+32,656) near the start of intron IX has been found to be associated with high IgE levels, while the deletion allele of a complex functional NOD1 indel polymorphism (ND1+32,656 * 1) is significantly correlated with early-onset inflammatory bowel disease." (PMID 36146565, 2022). "Variants in the candidate gene NOD1 (CARD4), which could be found to harbor a Lundehund specific ROH region, have been shown to be highly susceptible to inflammatory bowel disease." (PMID 27485430, 2016). "However, during DSS-induced colitis, the murine model of inflammatory bowel disease (IBD) that is driven by the microbiota, NOD1/NOD2-deficiency led to greater susceptibility to colitis." (PMID 24381573, 2013). "For instance, given the high regulation of NOD1/2 by ubiquitin and the contribution of NOD mutations to inflammatory diseases such as inflammatory bowel disease (IBD) or Crohn's disease, it is possible that DUBs could be used as a target in NOD-associated inflammatory conditions." (PMID 27597804, 2016). "There are exceptions with odds ratios of 3.9 and 2.5 reported for variants of NOD1 and IL23R on the risk of inflammatory bowel disease (IBD) while the distribution of effect sizes for the remaining 69 variants associated with Crohn's disease ranged from 1.04 to 1.74." (PMID 23982303, 2014). "Impaired NOD1/2 signalling may thus be a unifying immune defect in these patients and may contribute to the pathogenesis of XLP2, in particular to the inflammatory bowel disease." (PMID 23818254, 2013). "Indeed, human IECs constitutively express TLR3, TLR5, TLR9, NOD1, NOD2 and low levels of TLR2 and TLR4, where TLR4 is increased in inflammatory bowel disease (IBD) IECSs and intestinal macrophages." (PMID 36296363, 2022).
inflammatory bowel disease (continued). "Genetic variations in NOD1/CARD4 and/or NOD2/CARD15 have previously been identified in many diseases such as inflammatory bowel disease, Crohn’s disease, sarcoidosis, non-Hodgkin lymphoma, cancer and RA." (PMID 32578848, 2020).
colitis (24 papers, 2009 to 2025). Inflammation of the colon. "Nod1 can enhance the epithelial barrier function, promote intestinal homeostasis, and resist the invasion of pathogens that can cause colitis by regulating antimicrobial peptides (AMPs), proinflammatory cytokines, autophagy, and acquired immunity." (PMID 35954484, 2022). "To assess the potential contribution of the NLRs Nod1 and Nod2 in S. Typhimurium-induced intestinal inflammation, we tested the ability of wild-type S. Typhimurium to induce colitis in Rip2-deficient animals." (PMID 19662166, 2009). "NOD1 dysfunction resulted in inflammation, increasing the risk of colitis-associated colon cancer." (PMID 32021648, 2020). "Contrary to this, NOD1 deficiency has been shown to result in increased colitis-associated colonic cancer in a chemical colitis model, which may, in part, reflect differences in colitis modeling." (PMID 29515999, 2018). "Indeed, Nod1−/− mice show remarkable predisposition for tumor formation using a colitis-associated colon cancer model." (PMID 25594025, 2014). "The NOD1 expression in T cells could impede the colitis-associated intestinal tumorigenesis through mediating the IFN-γ signaling, and NOD2 could suppress the tumorigenesis of colitis-associated cancer by downregulating NF-κB and MAPK pathways with the induction of IRF4." (PMID 39135979, 2024). "In a mouse CRC model induced by the mutagen Azomethane (AOM) or the inflammatory agent sodium dextran sulfate (DSS), Nod1−/− mice show more severe colitis or tumor formation than wild-type (WT) mice." (PMID 35954484, 2022). "This idea is fully supported by our recent report in which NOD1 or NOD2-independent activation of RIPK2 mediates experimental colitis." (PMID 33935757, 2021). "Like Nod1−/− mice, NOD2-deficient mice have been revealed to be highly susceptible to DSS-induced colitis by inheritance of dysbiotic microbiota that markedly sensitizes mice to injury." (PMID 25071785, 2014). "NOD1 could protect the intestinal epithelial cells from injury, bacterial translocation, and colitis by regulating cell survival." (PMID 32021648, 2020). "Whereas a mutant sopE-deficient S. typhimurium strain did not elicit remarkable caecal inflammation, sopE-proficient S. typhimurium induced colitis in wild-type mice, but not in Nod1-deficient mice." (PMID 29738516, 2018). "Apart from various reports on mice, convincing data directly connecting NLRs and human CRC are available only for NOD1, NOD2 and NLPR3, which were found to be associated with susceptibility, progression and treatment of sporadic CRC, colitis and/or colitis-associated CRC." (PMID 29928061, 2018). "Similarly, infection of Nod1−/− and Nod1/Nod2 double-knockout mice revealed that both Nod1 and Nod2 play a protective role in S. Typhimurium ΔmsbB-induced colitis." (PMID 25423082, 2014). "Interestingly, the RIPK2-specific siRNA also diminished TNBS induced colitis in both NOD2-deficient and NOD1/NO2-double deficient mice, indicating the effect of RIPK2 on colitis was independent of either NOD1 or NOD2 signaling." (PMID 36959850, 2023). "Further analysis revealed that absence of NOD1 exacerbated NF-κB-mediated inflammation early during colitis causing gut barrier damage and prompted a second wave of microbiota driven inflammation and intestinal epithelial cell (IEC) proliferation, thus initiating tumor development." (PMID 25071785, 2014). "By being required for TLR9- as well as NOD1-mediated cytokine production, SLC15A4 has been shown to promote Th1-dependent colitis in vivo." (PMID 35562597, 2022). "NOD1 and NOD2 have both been defined as seminal players in gut homeostasis, providing protection against colitis and cancer." (PMID 25594025, 2014). "Our results indicate that S. Typhimurium ΔmsbB triggers exacerbated colitis in the absence of Nod1 and/or Nod2, which is likely due to increased TLR2 stimulation." (PMID 25423082, 2014).
colitis (continued). "may therefore have a confounding effect in mouse colitis models, particularly as H. muridarum was shown to engage TLR2 and NOD1, both of which are expressed in intestinal epithelial cells." (PMID 19401779, 2009). "Salmonella, for example, activates Nod1 in the gut through peptidoglycan (PGN) motifs which are the main component of its bacterial cell wall; the intestinal epithelium thus acts as a barrier against pathogen invasion, thereby limiting the severity of colitis or CRC." (PMID 35954484, 2022). "However, NOD1−/− mice do not exhibit any pathological differences to wild-type in a Salmonella-induced colitis model, whereas NOD1−/−NOD2−/− double knockout resulted in milder colitis." (PMID 29515999, 2018). "Furthermore, mice deficient of NOD1, NOD2 or double knockout mice for NOD1 and NOD2 are extremely susceptible to chemically-induced colitis due to increased barrier permeability and lack of efficient epithelial tissue repair." (PMID 24886810, 2014). "Interestingly, NOD1/NOD2-activation by the T3SS-1 effector SipA was shown to lead to a higher gut inflammation score in the colitis model as compared to mice lacking the receptors." (PMID 24381573, 2013).
Obesity (22 papers, 2013 to 2025). Accumulation of substantial excess body fat. "In the lung tissue, NOD1 deficiency during obesity led to elevated neutrophil accumulation, increased myeloperoxidase activity, reduced CD163+ macrophages, and enhanced β‐galactosidase activity." (PMID 40616268, 2025). "We investigated the role of macrophage nucleotide-binding oligomerization domain (Nod1) in obesity-associated diabetes using myeloid-specific Nod1-knockout mice (Nod1 floxed crossed with Lyz2Cre)." (PMID 40170862, 2025). "Our laboratory has studied the role of an immune receptor, nucleotide-binding oligomerization domain 1 (Nod1), in the context of obesity associated diabetes." (PMID 40170862, 2025). "In this work, we have examined the impact of a HFD in NOD1 deficient mice compared to wild-type (WT) mice during the early onset of diet-induced obesity." (PMID 32704052, 2020). "NOD1 shapes lung inflammation during obesity‐associated acute lung injury in female mice." (PMID 40616268, 2025). "This thyroid situation is reversed under HFD, which may contribute to the increased obesity of NOD1 deficient mice." (PMID 32704052, 2020). "However, HFD favors a rapid and significant development of obesity, or at least overweight, caused by an enlargement of eWAT adipocytes and enhanced hepatic steatosis in NOD1 KO mice, whereas this situation is delayed in the WT counterparts." (PMID 32704052, 2020). "Thus, while alterations in p38 signaling may contribute to the inflammatory imbalance observed, the exact mechanisms underlying its regulation in the context of NOD1 deficiency and obesity‐associated lung injury warrant further investigation." (PMID 40616268, 2025). "Here, we demonstrate that NOD1 is required for lower lung inflammation during LPS‐induced acute lung injury during obesity." (PMID 40616268, 2025). "Together, these findings demonstrate that NOD1 plays a critical role in modulating LPS‐induced acute lung injury during obesity." (PMID 40616268, 2025). "Yahia (2021) showed that despite a reduction in the number of inflammatory cells in the BAL of both NOD1- and NOD2-deficient lean female mice, only NOD1 affected the respiratory function, which should be considered in future obesity studies." (PMID 39507249, 2024). "Preclinical studies have reported opposing results concerning the implication and role of NOD1 in the promotion and severity of obesity." (PMID 38397943, 2024). "Ovalbumin (OVA)-induced lung inflammation was similar in female Nod1−/− and wild-type mice during high-fat-diet-induced obesity, but allergic lung inflammation was higher in obese, high-fat-diet-fed female Nod2−/− mice." (PMID 39507249, 2024). "In vivo experiments confirmed the detrimental role of NOD1 in obesity, as Nod1 and Nod2 double KO mice showed reduced HFD-induced IR, lipid accumulation, adipocyte size and inflammation in liver and AT compared to WT mice on HFD." (PMID 37239938, 2023). "This suggests that a complex interplay between immune cells and adipocytes accounts for the NOD1-mediated effects in obesity and IR." (PMID 37239938, 2023). "Still, little is known about the interplay between NOD1 and NOD2 and possible antagonistic effects, and the molecular determinants that are causal for the activation of NOD1 and NOD2 in obesity." (PMID 37239938, 2023). "Of the 22 human NLRs known to date, six proteins (NLRP3, NLRP6, NOD1, NOD2, NLRC5 and NLRP12) have been described to be associated with obesity and low-grade inflammation and one (NLRP3) with postprandial inflammation." (PMID 37239938, 2023). "In the context of obesity, only NOD1 expression is further upregulated in BAT from mice fed a HFD or in genetically obese (ob/ob) mice." (PMID 33503814, 2021). "In agreement with the body weight increase of NOD1 KO mice, a very significant enlargement of adipocytes was observed, indicating obesity or at least overweight." (PMID 32704052, 2020).